ENTPD1 (ectonucleoside triphosphate diphosphohydrolase 1)
Diseases named in the same sentence as ENTPD1 in open-access papers (continued):
Sharing a sentence is not in itself a finding about the gene and the disease.
tumor (continued). "Analysis of published single-cell RNA sequencing datasets of human GBM showed high enrichment of ENTPD1 expression in macrophages and moderate enrichment in malignant tumor cells." (PMID 36245000, 2022). "Subclusters with Entpd1 expression were assigned as tumor-specific T cells, including Treg (CD4+Foxp3+), CD8+ effector (Gzmb+Prf1+Ifng+), CD8+ effector memory (Cd44+Cd69+), CD8+ exhausted subclusters (Pdcd1+Lag3+Tigit+Havcr2+)." (PMID 36209176, 2022). "It was demonstrated that ENTPD1 high expression positively correlated with tumor stage in squamous cell carcinoma of the head and neck, and led to an inferior patients’ overall survival." (PMID 34465393, 2021). "Most of TEX cells were likely tumor-reactive T cells because of high levels of CD39 (ENTPD1) and CD103 (ITGAE) and very low level of KLRG1 38–41." (PMID 34489433, 2021). "Another study indicated that ENTPD1 was abundantly expressed in liver metastases and tumor draining lymph nodes from metastatic rectal adenocarcinoma." (PMID 34465393, 2021). "This is expected as ENTPD1 is an integral component of regulatory T cells, which infiltrate into the tumor stroma." (PMID 34502178, 2021). "CD39 (also termed ectonucleoside triphosphate diphosphohydrolase-1 or ENTPD1) is expressed or overexpressed in some types of neoplasms, and is reportedly involved in the immunosuppressive mechanism via its extracellular adenosine triphosphate (ATP) metabolism." (PMID 32203145, 2021). "We also analyzed scRNA-seq data from three GEO datasets (GSE140228 (10X), GSE140228 (Smartseq2) and GSE125449) and found that tumor-infiltrating macrophages expressed a high degree of CD39 (ENTPD1) among all immune cell types." (PMID 34838121, 2021). "ENTPD1 (expressed on tumor-specific T cells), as well as the cytotoxic factors granzyme B (GZMB) and perforin 1 (PRF1), expressed by T cells and NK cells, showed progressive decrease." (PMID 33276569, 2020). "In these mice, a higher expression of ENTPD1/CD39 was observed, culminating in an immunosuppressive environment along with increased Treg infiltration that contributes to tumor development." (PMID 33324568, 2020). "Altogether, these results suggest that ENTPD1/CD39 on Tregs has a key immunosuppressive role that ultimately promote tumour growth." (PMID 32859050, 2020). "In HCC, we observed increased expression of several more activation- (IFNG, CD38, IL2RA, TNFRSF9) and exhaustion-related (TIGIT, CTLA4, PDCD1, ENTPD1) genes in tumor MAIT cells." (PMID 32849590, 2020). "A subset of the potentially exhausted CD8+ T cells also showed the expression of Entpd1 (CD39), which was recently identified as a marker to distinguish tumor-specific and bystander CD8+ T cells." (PMID 32433953, 2020). "Nucleoside triphosphate diphosphohydrolase-1 (ENTPD1/CD39) is the rate-limiting enzyme in a cascade leading to the generation of immunosuppressive adenosine and plays an important role in tumor progression." (PMID 27749555, 2016). "Mutation-associated neoantigen (MANA) -specific CD8+ tumor-infiltrating lymphocytes (TIL) have been shown to express high levels of CXCL13 and CD39 (ENTPD1), and low IL-7 receptor (IL7R) levels in many cancer types, but their collective relevance to T cell functionality has not been established." (PMID 39900903, 2025). "Interestingly, known markers of activated (TIGIT, LAYN and HAVCR2) and tumor-reactive T cells (ENTPD1) were segregated into different clusters." (PMID 38724668, 2025). "Finally, ENTPD1 (encoding CD39, a marker associated with tumor-reactive T cells) was elevated only in the tumor specimens of su001." (PMID 40314973, 2025). "Several checkpoint and inhibitory receptors, such as PD-1 (gene name: PDCD1), CTLA4, TIM-3 (HAVCR2), LAG3, CD39 (ENTPD1), CD160, KLRG1, CD96, BTLA, 2B4, and TIGIT, have been implicated in the reduction of immune activity and response in the tumor micro-environment." (PMID 39513882, 2024).
tumor (continued). "In the ENTPD1/ITGAE double positive (tumor‐reactive, tr) population, local TCR clonal expansion and PD‐1 expression were used to classify the following four clusters of effector T cells (Teff): the TOP2A+ proliferating prTeff, IFNGhigh trTeff, IFNGlow trTeff, and IFNG−/CXCR6+ trTeff (trTeff‐CXCR6)." (PMID 38582099, 2024). "In CD8+ clusters, ENTPD1 (CD39) was more expressed in T-cells with high clonality (HC) compared to T-cells with low clonality (LC), but only in certain clusters over-represented in a given tumor i.e. clusters #3, #4, #11, #21." (PMID 38057799, 2023). "Moreover, T regulatory (Treg) cell upregulation of ENTPD1/CD39 within the tumor microenvironment generates immunosuppressive activity thereby facilitating malignant growth and survival." (PMID 36051466, 2022). "In addition, CD4+FOXP3+ regulatory T cells activated the CD39/ENTPD1 pathway and promoted hepatic metastatic tumor growth in mice." (PMID 36185217, 2022). "FOXP3 regulates the expression and infiltration of ENTPD1 to promote the occurrence of tumours." (PMID 36160018, 2022). "ENTPD1 methylation was obviously lower in primary tumor than the normal tissue (P< 0.001)." (PMID 34465393, 2021). "Furthermore, exhausted clusters specifically expressed tumor-reactive T cell markers (ENTPD1 and ITGAE), while the effect cluster rarely expressed them, indicating that cells belonging to the effect cluster were potentially bystander cells." (PMID 34804045, 2021). "However, the study surprisingly found that patients with higher ENTPD1 density in tumor cells were more likely to have favorable characteristics (early TNM and N stages) and better overall survival." (PMID 34465393, 2021). "Therefore, we can design the strategies for tumor treatment using the inhibitors of ENTPD1 or the inducer of autophagy to decrease the recruitment of Treg cells." (PMID 30678689, 2019). "These include NT5E (CD73) and ENTPD1 (CD39) which are involved in immunosuppressive adenosine signaling, LGALS1 (galectin-1) and TGFB1, which encode for anti-inflammatory cytokines, and CD274 (PD-L1), which binds to PD-1 to initiate an inhibitory signaling pathway in anti-tumor immune cells." (PMID 40277917, 2025). "Additionally, T regulatory (Treg) cells may upregulate ENTPD1/CD39 in the tumor microenvironment resulting in immunosuppression and promotion of tumor growth." (PMID 37684649, 2023). "Another mechanism in the tumor environment leading to exhausted T cells is the increased production of adenosine via sequential hydrolysis of adenosine-triphosphate (ATP) by the ectonucleoside triphosphate diphosphohydrolase-1 (CD39) and the ecto-5’-nucleotidase (CD73)." (PMID 35326415, 2022). "Previous work has indicated TGFβ may upregulate ENTPD1/CD39 in immunosuppressive myeloid cells, such that Vigil’s effect in downregulating TGFβ may counter this effect and account for its activity in patients with high tumor expression of ENTPD1/CD39." (PMID 36051466, 2022). "ENTPD1, also known as CD39, is an immune regulatory molecule in the tumor microenvironment through the breakdown of extracellular ATP and the production of adenosine." (PMID 40278994, 2025). "These nominated clusters upregulated key marker genes of activation, dysfunction, and differentiation that have been used to identify tumor specificity, such as CXCL13, TIGIT, PDCD1 (PD1), ENTPD1 (CD39), TOX, HAVCR2 (TIM-3), and LAG3." (PMID 40848148, 2025). "CD8+ T cells that exhibited high expression levels of exhaustion gene (HAVCR2, ENTPD1, LAG3, PDCD1, CXCL13, TOX, and GZMB) in the primary tumor were extracted and clustered." (PMID 40364834, 2025). "DUSP4 is implicated in the development of T cell exhaustion, and we also identified overexpression of several other classically defined exhaustion marker genes such as ENTPD1, IL2RA, and CXCR6, consistent with an immune-exhausted tumor microenvironment." (PMID 40848148, 2025).
tumor (continued). "The expression of ectonucleoside triphosphate diphosphohydrolase 1 (ENTPD1/CD39), which is a well-studied ATPase involved in ATP–adenosine metabolism, has been thoroughly described in tumor-infiltrating immune cells." (PMID 38755598, 2024). "Tregs, utilizing their elevated expression of CD39 and CD73, which are also named ectonucleoside triphosphate diphosphohydrolase 1 (NTPDase1) and 5’-nucleotidase separately, to metabolize ATP and ADP within the tumor microenvironment into AMP." (PMID 38500876, 2024). "It was found that the farther away from the tumor in TME, the higher the expression level of ENTPD1." (PMID 39256364, 2024). "This was also accompanied by the upregulation of proliferation marker MKI67, costimulatory genes (CD28, TNFRSF9 (4-1BB), and tumor-reactivity markers (e.g., ENTPD1/CD39, ITGAE/CD103) suggestive of an anti-tumor response in face of rising tumor levels." (PMID 37919606, 2024). "Conversely, FAT-WT patients had suppressive TME with high expression of CCL2, CXCL12, CXCL14, CD40, ENTPD1, TGFB1, and VEGF; these factors have been confirmed to promote angiogenesis, invasion, and metastasis of tumor cells." (PMID 35836939, 2022). "Treatment with 32-134D also inhibited hypoxia-induced expression of SLC2A1, LDHA, ENTPD1, and CA9 mRNA, which play roles in both tumor metabolism and immune evasion (P < 0.05)." (PMID 35499076, 2022). "Tumor-resident CD103+ TRM expressed a unique genotype compared to non-tumor CD103+ TRM, characterized by expression of ENTPD1 (CD39)." (PMID 32471032, 2020). "ENTPD1/CD39 and CD73 are the major ectonucleotidases expressed by tumor endothelial cells and Tregs." (PMID 30941139, 2019). "Ectonucleoside triphosphate diphosphohydrolase 1 (ENTPD1/CD39) and 5′-nucleotidase (NT5E/CD73) are located in the tumor cell membrane and impair antitumor T-cell responses by converting adenosinetriphosphate to adenosine." (PMID 25504435, 2014). "Their proliferating CD4+ counterparts upregulated ENTPD1 (CD39) and ITGAE (CD103), like proliferating CD8+ T cells, and hence this mobilized population is enriched for putative tumor antigen specificity." (PMID 40299576, 2025). "Altogether, these data suggest that HCC is characterized by a prevalence of tumor-activated Tregs and low not suppressive Tregs subpopulation, high ENTPD1+Tregs and MDSCs infiltration, and designing a more immunosuppressive TME in HCC as compared to CRLM." (PMID 37142825, 2024). "Thus, functional Tregs accumulate at the tumor site in both tumors, but in HCC Tregs displayed a stronger immunosuppressive phenotype as suggested by higher expression of ENTPD1." (PMID 37142825, 2024). "ENTPD1, IL17A, and P2RX7 were downregulated, while HSP90AA1, PIK3CA, and NT5E were upregulated, indicating that ENTPD1, IL17A, and P2RX7 might negatively affect tumor development and result in better outcome." (PMID 37587188, 2023). "Moreover, to verify the protein expression of the four genes, including ENTPD1, NLRP3, TLR4, P2RX7, the HPA database was applied for inspection of the expression of the proteins deprived from them in LUAD tumor tissues and normal tissues." (PMID 37553698, 2023). "Moreover, ENTPD1 (CD39) was higher expression in the Trm cluster, demonstrating that Trm cells were reactive tumor-infiltrating lymphocytes (TILs) distinct from bystander T cells." (PMID 37675100, 2023). "Additionally, some IRGs with copy number amplification (HMGB1, IL17RA, and BAX) showed increased expression in tumor tissues, while some IRGs with copy number deletions (IL10, NT5E, and ENTPD1) showed decreased expression in tumor tissues." (PMID 36386817, 2022). "We further verified the expression levels of ADAMTS9, ENTPD1, FRMD3, PRR15, AKAP12 in THCA, and the results of GEPIA database showed that ENTPD1, FRMD3, PRR15 were obviously increased in tumor tissues (n=512) compared with normal tissues (n=337), and the difference was statistically significant." (PMID 35756646, 2022).
tumor (continued). "Complementing the hypothesis that cDC1s migrate in the tumor through the XCL1/2 – XCR1 axis, we show that, besides for NK-cells, XCL1/XCL2 were also expressed by a subpopulation of ENTPD1+ ITGAE+ CD8+ T-cells." (PMID 36741389, 2022). "Whereas AL139147.1 showed a novel positive correlation with ENTPD1 (CD39) and IL1R1, which are involved in tumor immune cells infiltration and tumor microenvironment alteration; AC131391.1 correlated with LY96, which plays a vital role in tumorigenesis by modulating host immunity." (PMID 36313374, 2022). "The presence of ENTPD1/CD39 in multiple cell types other than certain cancers (e.g., CD4 + / Treg, CD8 + and MDSC) supports the consideration of therapeutic assessment of combined ENTPD1/CD39 inhibition and Vigil in patients with ENTPD1/CD39high tumor expression." (PMID 36051466, 2022). "These genes were defined as the tumor reactive signature (TRS), including co-inhibitory receptors (CTLA4, PDCD1, TIGIT and HAVCR2), reactive markers (CD38 and ENTPD1), effector molecules (NKG7 and PRF1), tumor necrosis factor TNFRSF9 and critical exhaustion-related regulator TOX." (PMID 34804045, 2021). "Studies have demonstrated the positive role of multiple biomarkers such as tumor mutation burden (TMB), the abundance of tumor-infiltrating immune cells (TICs), and the expression level of PD-L1 and CD39 (also known as ENTPD1) in predicting the response rate to immune checkpoint inhibitors (ICIs)." (PMID 35004669, 2021). "CD39 (also known as ectonucleoside triphosphate diphosphohydrolase-1, ENTPD1ase) and CD73 (also known as ecto-5′-nucleotidase, Ecto5′NTase) are ectonucleotidases expressed on the surface of tumor cells and immune cells for the metabolism of nucleotides." (PMID 34502359, 2021). "Notably, some genes related to exhaustion were also overexpressed in tumor‐infiltrating Tregs including TYMS, KIAA0101, CXCL13, CD27, HLA‐DQB1, HLA‐DMA, ENTPD1, CD200, DUSP4, and ZBED2." (PMID 32659053, 2020). "Ectonucleotidases are localized on tumor cells and different populations of immune cells that hydrolyze ATP or ADP into AMP via CD39 (ectonucleoside triphosphate diphosphohydrolase-1) and further process AMP into adenosine via CD73 (ecto-5′-nucleotidase) in the tumor microenvironment." (PMID 32005273, 2020). "Independently, increased mRNA expression of ENTPD1 (CD39) and NT5E (CD73) in the CD8− inflamed tumor subtype could signal an adenosine-rich TME, further contributing to CD8+ T cell exclusion in these tumors." (PMID 31675502, 2019). "To address whether the tumor inhibitory effects of POM-1 are mediated through ENTPD2, we inoculated Entpd1 KO HCC cells into C57BL/6 mice." (PMID 28894087, 2017). "Interestingly, although ENTPD1 and ENTPD2 share similar functions, demonstrated by ENTPD1- and ENTPD2-KO tumor models, ENTPD2 had greater effects on tumor growth, implying that ENTPD2 took the major role in HCC progression." (PMID 28894087, 2017). "In here, Tregs expressing CTLA-4, ICOS, ENTPD1, CD45RA and PD-1 were the majority among tumoral Tregs and the so called effector Tregs, CD25hiFOXP3hiCD45RA- highly suppressive cells, were the most represented among tumor Tregs tissue derived." (PMID 29100374, 2017). "CD36 also exhibited positive correlations with several immunostimulators, including C10orf54, CXCL12, ENTPD1, CD28, and TNFSF18, suggesting that it may contribute to immune activation pathways and modulation of antitumor immune responses in the tumor microenvironment." (PMID 41550652, 2025). "CD36 also demonstrated positive correlations with immune checkpoint molecules, including C10orf54, EDNRB, TLR4, ENTPD1, IL10, and IL2RA, suggesting that it may contribute to immune escape mechanisms by engaging checkpoint pathways in the tumor microenvironment." (PMID 41550652, 2025).
tumor (continued). "Further, upregulated expression of CD39 (ENTPD1) was detected, a marker of persistent TCR stimulation on exhaustive T cells, co-expression of which with tissue-resident memory T cell marker CD103 (ITGAE) has been identified on tumor-reactive CD8-positive T cells in human solid cancers." (PMID 36341460, 2022). "ENTPD1 was excluded as an FME target as we saw it was expressed in the tumor microenvironment." (PMID 34502178, 2021). "Ectonucleoside triphosphate diphosphohydrolase 1 (ENTPD1/CD39) is not the only ATP-degrading enzyme that is expressed by tumor cells; for example, nucleoside triphosphatase, cancer-related (NTPCR) is also expressed by some tumors which can bind to extracellular ATP and then convert it to adenosine." (PMID 34220957, 2021). "In contrast, the absence of 5'-nucleotidase (CD73), ectonucleoside triphosphate diphosphohydrolase 1 (CD39) and Cytochrome C was observed on these isolated tumor-derived exosomes." (PMID 24978137, 2014).